SEC1P (secretory blood group 1, pseudogene)
Synonyms: SEC1
Gene: Transcribed unitary pseudogene on chromosome 19 (48,673,174 to 48,681,047, forward strand). Ensembl gene ENSG00000232871.
Diseases named in the same sentence as SEC1P in open-access papers:
SEC1P is named in the same sentence as 3 diseases in open-access papers, as found by Europe PMC text mining. Sharing a sentence is not in itself a finding about the gene and the disease. The quoted sentences say what the papers report.
cancer (1 paper, 2020). A tumor composed of atypical neoplastic, often pleomorphic cells that invade other tissues. "Because SEC1P can be detected in multiple cancer cell lines, expression of the FUT2 and SEC1P fusion is expected in tumors in vivo." (PMID 32042317, 2020).
SEC1P also shares sentences with these, for which no sentence is quoted: leukemia (1 paper); tumor (1).